MIR3910-2 (microRNA 3910-2)
Synonyms: hsa-mir-3910-2; mir-3910-2
Gene: MicroRNA gene on chromosome 9 (91,636,264 to 91,636,345, reverse strand). Ensembl gene ENSG00000283351.
Diseases named in the same sentence as MIR3910-2 in open-access papers:
MIR3910-2 is named in the same sentence as 1 disease in open-access papers, as found by Europe PMC text mining. Sharing a sentence is not in itself a finding about the gene and the disease.
MIR3910-2 shares sentences with these, for which no sentence is quoted: autism (1 paper).